RN7SKP231 (RN7SK pseudogene 231)
Gene: Miscellaneous RNA gene on chromosome 8 (91,594,965 to 91,595,241, forward strand). Ensembl gene ENSG00000200151.
Homologues: Orthologues: chimpanzee 7SK (99% identical), guinea pig 7SK (72% identical), guinea pig 7SK (70% identical), mouse Gm55320 (60% identical). Paralogues in human: RN7SKP255 (82% identical), 7SK (81% identical), RN7SKP203 (81% identical), RN7SKP90 (81% identical), RN7SKP37 (81% identical), RN7SKP176 (80% identical), RN7SKP72 (80% identical), RN7SKP79 (80% identical), RN7SKP180 (80% identical), RN7SKP87 (80% identical), RN7SKP9 (80% identical), RN7SKP134 (79% identical), and 284 more.